RNU6-719P (RNA, U6 small nuclear 719, pseudogene)
Gene: Small nuclear RNA gene on chromosome 7 (39,768,341 to 39,768,444, forward strand). Ensembl gene ENSG00000252480.
Homologues: Orthologues: chimpanzee U6 (100% identical), macaque U6 (90% identical), pig U6 (81% identical), pig U6 (77% identical), dog U6 (76% identical). Paralogues in human: RNU6-1052P (99% identical), RNU6-1319P (96% identical), RNU6-241P (96% identical), RNU6-747P (96% identical), RNU6-1076P (95% identical), RNU6-1100P (95% identical), RNU6-1118P (95% identical), RNU6-1217P (95% identical), RNU6-355P (95% identical), RNU6-447P (95% identical), RNU6-785P (95% identical), RNU6-791P (95% identical), and 1285 more.